VCAM1 (vascular cell adhesion molecule 1)
Diseases named in the same sentence as VCAM1 in open-access papers (continued):
Sharing a sentence is not in itself a finding about the gene and the disease.
glioma (continued). "Treatment of human umbilical vein ECs (HUVECs) with CM from oHSV-infected glioma cells increased expression of EC activation surface receptors: CD54 (ICAM1), CD106 (VCAM1), and CD62P (P-selectin)." (PMID 36789106, 2023). "In CD204−/− glioma, the number of VCAM1+ TAMs and CCR2+ TAM precursor cells was significantly elevated compared to CD204+/+ glioma." (PMID 36686729, 2022). "In our study, we found that the expression of VCAM1, ICAM1, CDH2 was down-regulated, while the expression of SDC2 was up-regulated after knocking down the expression of GNG5 in glioma cells." (PMID 34098960, 2021). "To investigate the impact of the increased levels of the TNF-α expression on EC activation in GL261 syngeneic glioma mouse model, we performed double IHC staining with CD31 and VCAM1 antibodies." (PMID 33853689, 2021). "The main targets identified for the treatment of glioma are transferrin (Tf), folate, EGFR, vascular endothelial growth factor (VEGF), αvβ3 integrins, matrix metalloproteinases (MMP), and vascular cell adhesion molecule 1 (VCAM-1)." (PMID 29751640, 2018). "In this study, we investigated and revealed a differential expression of VCAM-1 between the TMZ-resistant and the parental glioma cells." (PMID 29301329, 2018). "Thus anti-VCAM-1 treatment may present a potential strategy for the therapy of gliomas." (PMID 23593320, 2013). "We further showed that expression of VCAM1 is high in high grade gliomas but low or absent in low grade gliomas." (PMID 33853689, 2021). "We analyzed SIRT1, CCL2, VCAM-1 and ICAM-1 in human glioma cell lines by immunoblotting." (PMID 31207928, 2019). "FACS measurements showed increased VCAM1-positive TAMs and CCR2+ TAM precursor cells in Sr-a1−/− glioma compared with Sr-a1+/+ glioma, confirming that SR-A1 deletion could increase TAM infiltration." (PMID 27367025, 2016). "In reconciling these observations, we determined that the putative IL13Rα2-specific antibody B-D13 recognizes VCAM-1, and that cytokine induction is not a viable approach to increase cell surface expression of IL13Rα2 for therapeutic targeting of gliomas." (PMID 24787244, 2014). "Nevertheless, the role of VCAM-1 in the migration and invasion of glioma cells has not been clearly identified." (PMID 23593320, 2013). "VCAM-1 is highly expressed in both gliomas and the surrounding normal brain tissue." (PMID 39201395, 2024). "Instead we demonstrate by immunoprecipitation experiments and mass spectrometry that the antigen recognized by the B-D13 antibody following cytokine stimulation is VCAM-1, and that VCAM-1, but not IL13Rα2, is induced on glioma cells by TNF alone or in combination with IL-13 or IL-4." (PMID 24787244, 2014). "Glial Tumors Group: Notably, E-Selectin, ICAM-1, PAI-1, MMP-9, and eNOS were expressed predominantly, whereas VCAM-1 showed lower expression, and P-Selectin was not expressed." (PMID 38306519, 2024). "GSE4290 indicated that VCAM-1 and ICAM-1 levels were higher in the grade four glioma group than in the low-grade glioma and non-tumor group." (PMID 31207928, 2019). "Because the levels of vWF, MMP9, VCAM1, angiogenin, and HGF were increased in both GBM and MI patients, but not in the lower-grade gliomas, these factors seem to be necessary for neovascularization in general, both under reactive and high-grade neoplastic conditions." (PMID 31428150, 2019).
ovarian carcinoma (34 papers, 2012 to 2025). A malignant neoplasm originating from the surface ovarian epithelium. "A two-marker panel of CA-125 and VCAM-1 showed strong diagnostic performance and improvement over the use of CA-125 alone in detecting recurrent ovarian cancer." (PMID 37357306, 2023). "Vascular cell adhesion molecule-1 (VCAM-1) is associated with ovarian cancer progression but the origin of its soluble form (sVCAM-1) in serum is not well investigated." (PMID 25177246, 2014). "Regarding vascular permeability, M2 macrophages seemed to contribute to vascular permeability via the VCAM1/RAC1/ROS/p-PYK2/p-VE-cadherin cascade initiated by interaction between VLA4 and VCAM-1 on endothelial cells in ovarian cancer." (PMID 40071851, 2025). "Logistic regression modeling selected a two-marker panel of CA-125 and VCAM-1 that improved the performance of CA-125 alone in detecting recurrent ovarian cancer (AUC: 0.813 versus 0.700)." (PMID 37357306, 2023). "In our study, serum VCAM-1 levels were found to be significantly elevated in ovarian cancer (as well as recurrent tumors) when compared to healthy controls." (PMID 37357306, 2023). "VCAM-1 expression in mesothelium is corelated with shortened overall survival of epithelial ovarian cancer (EOC) patients." (PMID 36497180, 2022). "For VCAM1, intact N-glycopeptides along with the Asn365 glycosite were found to be upregulated in the ovarian cancer SKOV3 cells." (PMID 36482940, 2022). "In ovarian cancer, there is a strong correlation between the VCAM1 expression level and ascite volume." (PMID 36482940, 2022). "We did not observe upregulation of prototypical endothelial cell markers (CD31, CD34, VE-cadherin, Icam1, and Vcam1) upon ectopic expression of FOXC2 in mouse ovarian cancer cells." (PMID 36230774, 2022). "The role VCAM-1 in ovarian cancer is largely unclear, but it has been shown that mesothelial expression mediates tumour cell invasion." (PMID 32933568, 2020). "Expressed on activated endothelial and mesothelial cells VCAM-1 has been identified as an important mediator for adhesion of ovarian cancer cells to and invasion through the mesothelium." (PMID 32933568, 2020). "The other important adhesion molecule which interact with ovarian cancer cells and the mesothelial cells is α4β1-integrin and vascular cell adhesion molecule-1 (VCAM-1) because VCAM-1 is preferentially expressed on the mesothelium of ovarian cancer cells." (PMID 28698469, 2017). "Function-blocking antibodies against VCAM-1 and α4β1-integrin block the migration and metastasis of ovarian cancer cells in a xenografted model." (PMID 28698469, 2017). "The interaction of mesothelial VCAM-1 with its ligand α4β1 integrin is critical for mesothelial cell clearance and ovarian cancer metastasis." (PMID 25886093, 2015). "Previously, we demonstrated a role for VCAM-1 expressed on the mesothelium in the regulation of ovarian cancer invasion in vitro and in vivo." (PMID 25769037, 2015). "α4β1-integrin expressed on ovarian carcinoma cells binds to VCAM-1, which is present on the mesothelial cells and function-blocking antibodies directed against VCAM-1 and α4β1-integrin block migration and metastasis in a xenograft model." (PMID 22235205, 2012). "In this study, we evaluated a panel of 8 biomarkers, including B7-H3, IL-6, PLA2G7, Tie-2, GDF-15, IL-6 R alpha, sSDC1, and VCAM-1 selected based on their reported relevancy to ovarian cancer and multiplexing feasibility as a customized magnetic bead-based 8-plex immunoassay." (PMID 37357306, 2023). "In addition, VCAM-1 expression correlated with tumorigenesis and poor prognosis in ovarian cancer, and higher preoperative serum sVCAM-1 concentrations in ovarian cancer patients were linked to early tumor recurrence or disease progression." (PMID 37357306, 2023).
ovarian carcinoma (continued). "At a fixed specificity of 83%, the two-marker panel significantly improved sensitivity in separating primary from recurrent tumors (70.8% versus 37.5%, P = 0.004), demonstrating that VCAM-1 was significantly complementary to CA-125 in detecting recurrent ovarian cancer." (PMID 37357306, 2023). "A two-marker panel of CA-125 and VCAM-1 was further identified to detect recurrent ovarian cancer." (PMID 37357306, 2023). "Furthermore, the expression of VCAM1 correlates with poor prognosis in ovarian cancer, especially in the high grade of serous ovarian cancer." (PMID 36482940, 2022). "In addition to BC, VCAM-1 increased expression has also been described in other cancer types such as glioblastoma, gastric and ovarian cancer." (PMID 31340603, 2019). "However, it was observd that VCAM-1 was lower in early-stage ovarian cancer compared with healthy women, and there was a significant difference between patients with early-stage and late-stage ovarian cancer in their study." (PMID 37357306, 2023). "Simvastatin has been found to reduce ovarian cancer cell adhesion to peritoneal mesothelial cells through decreased expression of VCAM-1 and β1 integrin in vitro, suggesting that simvastatin may provide a novel therapeutic approach to the prevention of peritoneal carcinomatosis." (PMID 26503475, 2016). "Our findings suggest that VCAM-1 and ICAM-1 play a role in ovarian cancer recurrence, with VCAM-1 significantly elevated in tumor tissue and blood of recurrent cases." (PMID 40652770, 2025). "Signal intensities for the quantified proteins overall spanned approximately seven orders of magnitude and included several previously reported ovarian cancer marker candidates, such as HE4, MSLN, VCAM-1, CEA, CRP, PROZ, LCAT, and M-CSF." (PMID 36669591, 2023). "Using VCAM-1-specific imaging probes, VCAM-1 expression was identified as a potential marker of ovarian cancer peritoneal metastasis and therapeutic response to platinum-based agents." (PMID 37357306, 2023). "In ovarian cancer, M2 macrophages promote the formation of ascites by reducing the expression of VLA4 in their cell membranes and reducing the level of VCAM1 in endothelial." (PMID 37005667, 2023). "Several genes have been confirmed to be closely related to the occurrence and progression of ovarian cancer, including SNAI2, VCAM1, BRCA1, MMP2, MECOM, MXS1, PARP1 and so on." (PMID 35090503, 2022). "Vascular cell adhesion molecule-1 (VCAM-1) is a known, highly expressed membrane protein on mesothelial cells and has been found to play a role in adhesion to the peritoneum in ovarian cancer." (PMID 36614904, 2022). "In a separate ovarian cancer study anti-ICAM-1 blocking antibodies only partly blocked CD8+ T cell infiltration, suggesting that additional molecules like VCAM-1 may mediate CD8+ T cell extravasation as well." (PMID 33262763, 2020). "These alterations were shown to facilitate the adhesion of ovarian cancer cells mainly via (i) exposure of submesothelial ECM, where cancer cells preferably adhere, and via (ii) upregulated expression of ICAM-1/VCAM-1, HA, and FN1, providing integrin- and CD44-mediated ovarian cancer cell adhesion." (PMID 33270665, 2020). "In clinical practice, VCAM-1 expression has been reported to be correlated with poorer outcome in TNBC but also in other cancer type such as glioblastoma and ovarian cancer, and VCAM-1 imaging has been proposed as a tool for the assessment of tumor aggressiveness." (PMID 31340603, 2019). "In this study, we showed that EVs from ovarian cancer cells upregulated genes related to the inflammatory response, including immune cell–attracting cytokines (CCL2, CCL3/L1, CCL15, CCL18, and CCL20), interleukins (IL1B and IL32), and cell–cell adhesion transcripts (VCAM1 and ICAM1)." (PMID 40689422, 2025).
ovarian carcinoma (continued). "Inflammatory cytokines in ovarian cancer cells, including tumor necrosis factor-α (TNF-α) and interleukin-1 (IL-1), promote malignant progression—such as tumor cell migration and invasion—by upregulating the expression of vascular cell adhesion molecule-1 (VCAM-1) and ICAM-1." (PMID 40140925, 2025). "At a fixed SP of 83%, the two-marker panel of CA-125 and VCAM-1 performed best in separating primary from recurrent tumors due to a significant improvement in the SN (70.8% versus 37.5%), demonstrating that VCAM-1 is complementary to CA-125 for the identification of recurrent ovarian cancer." (PMID 37357306, 2023).
multiple sclerosis (31 papers, 2011 to 2025). A progressive autoimmune disorder affecting the central nervous system resulting in demyelination. "For example, in multiple sclerosis (MS), miR-126 suppresses immune cell infiltration into the CNS by targeting vascular cell adhesion molecule 1 (VCAM-1), thereby reducing neuroinflammation-mediated fatigue." (PMID 40626047, 2025). "Although the role of VCAM-1 has been studied in various diseases, such as multiple sclerosis, a neuroinflammatory condition affecting the central nervous system, there is limited information concerning its involvement in retinal diseases." (PMID 38317227, 2024). "Although there are currently no clinically approved agents targeting VCAM-1, Natalizumab, an agent that targets α4β1 and effectively blocks VCAM-1-α4β1 interaction, has become one of the most effective therapies for multiple sclerosis." (PMID 38317227, 2024). "Immunofluorescence staining of human biopsy material from patients with multiple sclerosis revealed VCAM-1 at cuff borders and on astrocytes in demyelinating lesions." (PMID 37467333, 2023). "In various animal model experiments, VCAM-1 blockade reduces the severity of inflammatory reaction in atopic dermatitis, multiple sclerosis, and Crohn’s disease, mostly by blocking T cell infiltration into the affected tissues." (PMID 32397227, 2020). "For instance, Natalizumab, a monoclonal antibody targeting the interaction between very late antigen 4 (VLA-4) and VCAM-1, has been successfully developed as a treatment for multiple sclerosis." (PMID 25505871, 2014). "VCAM-1 plays a major role in multiple sclerosis, other autoimmune diseases as well as in the metastatic process." (PMID 24115947, 2013). "The VCAM-1 inhibition shown in the cerebral vasculature was interpreted as a new mechanism to explain the therapeutic effect of increased AEA tone in neuroinflammatory diseases such as multiple sclerosis." (PMID 39768198, 2024). "Cleaved VCAM-1 has been detected in human serum and CSF, with higher levels in multiple sclerosis; however, until now, the protease responsible for shedding was unknown." (PMID 37467333, 2023). "Interestingly, genetic variation in both VCAM1 and EXTL2 is associated with blood cell counts and multiple sclerosis, according to the GWAS catalog." (PMID 35754128, 2022). "Natalizumab, an integrin α4β1 (VLA‐4) antagonist that interferes with leucocyte trafficking by blocking the interaction between VLA‐4 and vascular cell adhesion molecule 1 (VCAM‐1), has been used in the therapy of inflammatory bowel disease and multiple sclerosis." (PMID 33230903, 2021). "This suggests that the AG variant may change the VLA-4 α4 subunit conformation, making it bind with higher affinity to its ligand VCAM-1, increasing the accumulation of T cells in chronic inflammatory diseases of the CNS, such as multiple sclerosis and AD." (PMID 31427644, 2019). "Therefore, the pathological molecules of BMECs, such as VCAM-1, can be targeted to treat multiple sclerosis." (PMID 29531265, 2018). "Furthermore the beneficial effects of WIN in a chronic model of multiple sclerosis were partially mediated by down-regulating adhesion molecules VCAM-1 and ICAM-1." (PMID 27158245, 2016). "Thus, the antibody disables the function of VCAM-1 and prevents the passage of macrophages and other myeloid cells into tissues such as the intestine in Crohn’s disease and the brain in multiple sclerosis." (PMID 24115947, 2013). "In an adapted multiple sclerosis murine model of EAE, VCAM-1 is upregulated; memory plasma cells are localized in areas of increased VCAM-1 expression." (PMID 31024553, 2019). "Similar to P-selectin, soluble Vcam1 in CSF and plasma correlates with BBB lesion severity, in multiple sclerosis (MS) for example." (PMID 29759062, 2018). "Vascular cell adhesion molecule-1 (VCAM-1), an endothelial receptor belonging to the immunoglobulin superfamily is a key player in leukocyte extravasation in multiple sclerosis (MS) [; rev]." (PMID 21851608, 2011).
multiple sclerosis (continued). "Targeting of VCAM-1 with VCAM-MPIO and in vivo MRI has previously been demonstrated in preclinical models of numerous diseases, including neuroinflammation, cardiovascular disease, multiple sclerosis, epilepsy, and, most recently, brain metastasis." (PMID 39000268, 2024). "The frequency of microglia expressing VCAM-1 is enhanced in oligodendrocyte injured regions in multiple sclerosis, while endothelial cells in spinal cord lesions were VCAM-1 negative, suggesting its participation in the demyelination process." (PMID 36052089, 2022). "In EAE, as well as in multiple sclerosis (MS), ICAM-1, VCAM-1, and ALCAM are upregulated." (PMID 32753493, 2020). "To define whether cleavage of VCAM-1 and NrCAM also play a role in human tissues, we analyzed the CSF of different patients with multiple sclerosis and age- and sex-matched, non-multiple sclerosis somatoform controls for gelatinase activity and the presence of soluble VCAM-1 or NrCAM." (PMID 37467333, 2023).